SMIM46 (small integral membrane protein 46)
Tractability: Antibody: UniProt predicts a signal peptide or a membrane-spanning region.
Gene: Protein-coding gene on chromosome 19 (14,112,324 to 14,112,476, reverse strand). Ensembl gene ENSG00000289762.
Subcellular location: Membrane
Gene Ontology:
Cellular component: membrane
Homologues: Orthologues: mouse Smim46 (74% identical).